IRAK1 (interleukin 1 receptor associated kinase 1)
Diseases named in the same sentence as IRAK1 in open-access papers (continued):
Sharing a sentence is not in itself a finding about the gene and the disease.
infectious disease (2 papers, 2021 to 2022). A disorder directly resulting from the presence and activity of a microbial, viral, or parasitic agent in humans. "We also noticed that apoptosis-related pathways (2 hypermethylation and 4 hypomethylation genes) including B cell leukemia/lymphoma 2 (Bcl2) and interleukin-1 receptor-associated kinase 1 (Irak1) and infectious disease were involved." (PMID 34884879, 2021).
Respiratory Diseases (2 papers, 2009 to 2024). "Next, complementary analyses identified nine DMGs (LTA, STAT3, IKBKG, IRAK1, NOD2, TLR2, TNFRSF1A, and IKBKB) that might be involved in the immune response of XJB cattle infected with respiratory diseases." (PMID 38732144, 2024).
heart disease (1 paper, 2022). "Because atherosclerotic-induced MI and bacterial-induced cardiac septic shock share common characteristics of myocardial dysfunction, pharmacological inhibition of IRAK1 may reduce cardiac inflammation and provide beneficial effects for patients with heart disease." (PMID 35345264, 2022).
neurodevelopmental disorder (1 paper, 2024). A behavioral and cognitive disorder with onset during the developmental period that involves impaired or aberrant development of intellectual, motor, or social functions.
neurological diseases (1 paper, 2020). "In addition, miR-146a participates in the neuroinflammatory response of different neurological diseases by regulating the common inflammation-related target genes (IRAK1, TRAF6, and CFH) and related pathways (TLR signaling pathway and complement activation pathway)." (PMID 32581706, 2020).
IRAK1 also shares sentences with these, for which no sentence is quoted: breast tumor (3 papers); periodontitis (3); Thrombocytopenia (3); colorectal cancer (2); Crohn disease (2); head and neck cancer (2); IgA nephropathy (2); metabolic disorders (2); multiple sclerosis (2); necrotizing enterocolitis (2); Oral Carcinoma (2); prion disease (2); thymoma (2); Waldenstrom macroglobulinemia (2); acute lung injury (1); acute pancreatitis (1); alcoholism (1); anemia (1); antiphospholipid syndrome (1); bacterial sepsis (1); brain diseases (1); brain injury (1); brain tumor (1); Burkitt lymphoma (1); C. perfringens infection (1); cerebral infarction (1); Chronic colitis (1); chronic myeloid leukemia (1); CNS lymphoma (1); common variable immunodeficiency (1).
A further 58 diseases each share a sentence with IRAK1 in 1 paper.